NQO1 (NAD(P)H quinone dehydrogenase 1)
Diseases named in the same sentence as NQO1 in open-access papers (continued):
Sharing a sentence is not in itself a finding about the gene and the disease.
acute lymphoblastic leukemia (8 papers, 2012 to 2023). Leukemia with an acute onset, characterized by the presence of lymphoblasts in the bone marrow and the peripheral blood. "In current study, we focused on one of rs1800566 polymorphism in the NQO1 gene, but in fact there had other sites that may affect tumor susceptibility, such as rs1131341, which were reported to be associated with an increased risk for acute lymphoblastic leukemias (ALL)." (PMID 36338728, 2022). "The association between the NQO1 C609T polymorphism and increased risk of AML and acute lymphoblastic leukemia (ALL) has also been reported." (PMID 26822308, 2016).
endometrial cancer (8 papers, 2015 to 2022). Primary or metastatic malignant neoplasm involving the endometrium (mucous membrane that lines the endometrial cavity). "Indeed, stigmasterol increases the sensitization of endometrial cancer cells to cisplatin by suppressing Nrf2, NQO1, and HO1 expression in a dose-dependent manner." (PMID 36290632, 2022). "It was found that SPL‐A could promote TRAIL‐induced apoptosis of endometrial cancer cells by regulating apoptosis‐related proteins and inhibiting NQO1 activity in vitro." (PMID 33841805, 2021). "Moreover, there was significant correlation between the high level of NQO1 and Nrf2 expression and high tumor grade in cervical and endometrial carcinoma cases." (PMID 28983331, 2015). "Based on this study and our study on endometrial cancer, we recommend follow-up of interactions between acrylamide intake and SNPs for ovarian and endometrial cancer risk, particularly SNPs in CYP2E1, GSTs, the HSD3B1/B2 gene cluster, AKR1C1, NQO1, GPX1 and MGC12965." (PMID 28391539, 2017). "A recent study reports that ES936, an NQO1 inhibitor, enhances TRAIL-induced apoptosis in endometrial carcinoma Ishikawa cells, and inhibition of NQO1 activity leads to the effect of SPL-A on TRAIL-induced apoptosis." (PMID 33087132, 2020).
squamous cell carcinoma (8 papers, 2012 to 2024). A carcinoma arising from squamous epithelial cells. "My previous research shows that hybrids of 1,4-naphthoquinone with a thymidine moiety, such as 11–12, show activity against two squamous cell cancer lines (SCC-9 and SCC-25), which exhibit different expression levels of the gene encoding the NQO1 protein." (PMID 39456992, 2024). "In contrast to a previous report that arsenic pollution-induced NRF2/NQO1 signaling regulates cell cycle progression at G1/S in squamous cell carcinoma 64, in the present study, we found that NQO1 regulates cell cycle progression at G2/M phase." (PMID 36793872, 2023). "We compared the mRNA levels of NQO1 in healthy lung tissue, adenocarcinoma (LuAD) and squamous cell carcinoma (LuSC) patients using the TGCA dataset." (PMID 32007910, 2020). "NQO1 is constitutively overexpressed in several cancers including breast, pancreatic, and squamous cell carcinomas." (PMID 31858276, 2019). "In this study, we aimed to investigate the clinicopathological significance of upregulated NQO1 protein expression in squamous cell carcinomas (SCCs) of the uterine cervix." (PMID 24912939, 2014). "Upon examination of squamous cell carcinomas samples mitotic figures were located and immunostaining for NQO1 was clearly visible on the mitotic spindles of these cells." (PMID 22984577, 2012). "NAD(P)H:quinone oxidoreductase 1 (NQO1), an enzyme overexpressed in squamous cell carcinoma, plays an important role in proliferation and chemoresistance." (PMID 31858276, 2019).
Stroke (8 papers, 2013 to 2025). Sudden impairment of blood flow to a part of the brain due to occlusion or rupture of an artery to the brain. "In human, a single nucleotide polymorphism (SNP) of GGCX gene is shown to be associated with risk susceptibility of stroke when combined with SNP of NAD(P)H:quinone oxidoreductase (NQO1) gene, which encodes a protein protective against oxidative stress." (PMID 35174198, 2021). "Several studies have shown that NQO1 expression and activity are altered in animal models of stroke as well as in patients with stroke." (PMID 38167027, 2024). "Following the administration of butylphthalide in patients with stroke, the serum levels of Keap1 were elevated, while the serum levels of NQO1, Nrf2, and ARE were reduced compared to those in the control group." (PMID 38167027, 2024). "Pharmacological and/or dietary induction of the Nrf2/HO-1/NQO1 pathway may serve as a therapeutic strategy to prevent oxidative stress-induced damage in the peripheral vessels or the blood–brain barrier in stroke." (PMID 38167027, 2024). "Interestingly, different natural compounds, owing to their ability to induce Nrf2 activation, showed beneficial actions in experimental stroke models, leading to the increased expression of antioxidant enzymes, including HO-1 and NQO1, and reducing oxidative stress markers." (PMID 32664226, 2020). "We have found that in stroke neuroprotection studies, inhibition of DLDH by 5-methoxyindole-2-carboxylic acid (MICA) was able to activate the Nrf2 signaling pathway that leads to NAD(P)H quinone dehydrogenase 1 (NQO1) upregulation." (PMID 30717346, 2019).
acute kidney injury (7 papers, 2017 to 2024). Sudden and sustained deterioration of the kidney function characterized by decreased glomerular filtration rate, increased serum creatinine or oliguria. "HSP increased Nrf2 signalling, SIRT6, NQO1, HO-1 expression, down-regulated SCr, blood urea nitrogen (BUN), MDA, MPO, GSH, SOD, NOX4 expression level, thereby relieving cisplatin-induced acute kidney injury." (PMID 35128104, 2022).
atherosclerosis (7 papers, 2013 to 2024). A disease characterized by the build-up of fatty material and calcium deposition in the arterial wall resulting in partial or complete occlusion of the arterial lumen. "A previous study in patients with ischemic stroke associated with large-artery atherosclerosis showed that NQO1*2 polymorphisms were connected with a lower risk of atherosclerosis-associated stroke." (PMID 34947831, 2021). "The NQO1 rs1800566 polymorphism is associated with coronary heart disease and atherosclerosis." (PMID 39174970, 2024). "In addition to oxLDL activated increases in HO-1 expression through Nrf2, other Nrf2 downstream targets appear to play a role in this process, like glutathione-cysteine ligase modifying subunit and NQO1, both of which have been associated with protection against atherosclerosis." (PMID 23691261, 2013). "The genetic pathways related to NQO1 were mainly enriched in ubiquinone and other terpenoid–quinone biosynthesis pathways, fluid shear stress, atherosclerosis, and the biosynthesis of cofactors." (PMID 39174970, 2024). "Pathway enrichment analysis showed that NQO1 and its related proteins were mainly involved in ubiquinone and other terpenoid–quinone biosynthesis, fluid shear stress, atherosclerosis, and biosynthesis of cofactors, which are all closely related to IS." (PMID 39174970, 2024). "However, it should be noted that NQO1 has also been reported as both an anti- and proatherogenic factor and therefore improved the understanding of the role of NQO1 in atherosclerosis susceptibility that may lead to clarification of Nrf2 influences on this process." (PMID 23691261, 2013). "Mice lacking HO-1 are more susceptible to myocardial infarction and atherosclerosis; mice lacking NQO1 are more susceptible to chemically induced carcinogenesis and chemical toxicity, and mice lacking G6PD exhibit increased renal oxidative stress and are more susceptible to myocardial dysfunction." (PMID 26885667, 2016). "In addition, our analysis found that NQO1 and NRF2 are involved in response to xenobiotic stimulus, fluid shear stress, and atherosclerosis pathways in cancer." (PMID 37583897, 2023). "Finally, Nrf2 could protect VSMCs against oxidative stress, and may protect against atherosclerosis progression by activation of athero-protective genes, such as HO-1 or NAD(P)H dehydrogenase quinone 1 (NQO1), which suppress proliferation of SMCs and VSMCs respectively." (PMID 34573095, 2021).
breast tumors (7 papers, 1997 to 2024). "Expression of NQO1 has been observed in the rat liver and in several tissues in humans, especially colon, pancreas, lung, and breast tumors, and the levels of NQO1 have been reported to be controlled by ARE in an oxidative stress environment." (PMID 34067204, 2021). "Tamoxifen treated mice had significantly increased the protein expression levels for Nrf2 and NQO1 in their breast tumors." (PMID 26883574, 2016). "Protein expression of NQO1 was studied by immunohistochemistry on tissue arrays of invasive breast tumor tissue." (PMID 18416817, 2008). "Immunohistochemical analysis of 354 invasive breast tumors revealed that NQO1 protein expression in a subset of breast tumors is higher than in normal epithelium, which contradicts its proposed role as a tumor suppressor gene." (PMID 18416817, 2008). "Indeed, we observed differences in the relative ability of BSO or β-lapachone to sensitize individual PDXs to phenformin treatment, suggesting that breast tumors likely differ in their reliance on glutathione and/or NQO1 to maintain redox balance." (PMID 34083537, 2021). "We also investigated NQO1 protein expression in 354 breast tumors." (PMID 18416817, 2008). "Pair-wise mRNA expression correlation analysis in human breast tumors from TCGA cohort showed a positive correlation between ZMYND8 and antioxidant genes including NQO1, GPX2, GCLC, GCLM, TXNRD1, and SRXN1." (PMID 38488001, 2024). "Those patients, who had ERα-positive breast tumors with low expression of Nrf2, ABCC1, ABCC3 and NQO1 at the time diagnosis, had a better prognosis after tamoxifen treatment than those patients that were high expressers, with an HR value as high as 4.2." (PMID 26883574, 2016). "These signature genes are densely connected, among which several, such as ESR1, FOXA1, NQO1, GATA1, ALDH3B2, keratins, are well-known players driving the heterogeneity and carcinogenesis of breast tumors." (PMID 26404658, 2015). "NQO1 and ATBF1 have previously been reported to be involved in carcinogenesis, and were therefore investigated in more depth in breast tumors in this study." (PMID 18416817, 2008). "Thus, evaluating breast tumors of patients for the expression of Nrf2, ABCC1, ABCC3 and NQO1 warrants formal assessment as predictive markers for tamoxifen response." (PMID 26883574, 2016). "Like NQO1, also HER2 overexpression was more prevalent in poorly differentiated breast tumors, which could explain this correlation." (PMID 18416817, 2008).
epilepsy (7 papers, 2020 to 2025). A brain disorder characterized by episodes of abnormally increased neuronal discharge resulting in transient episodes of sensory or motor neurological dysfunction, or psychic dysfunction. "NQO1 expression in the human epileptic brain may also be linked to the outcomes of epilepsy surgery." (PMID 38167027, 2024). "These experimental and clinical assessments indicate that NQO1 may be implicated in the pathophysiology of a wide range of both acute and chronic neurological disorders, including epilepsy, AD, PD, amyotrophic lateral sclerosis (ALS), MS, cerebrovascular diseases, and brain malignant tumors." (PMID 38167027, 2024). "The different modulation of NRF2 pathway intermediates, such as NQO-1 and HO-1, suggest that the effect of an early immune challenge can negatively modulate the hepatic oxidative balance during epilepsy." (PMID 39199203, 2024). "The administration of dimethyl fumarate, an activator of the Nrf2 pathway, significantly reduced seizures, suppressed pro-inflammatory cytokines, and enhanced the gene expression of Nrf2, NQO1, and HO-1 in the chemical kindling epilepsy rat model." (PMID 38167027, 2024). "DMF increased the expression of the downstream Nrf2 genes NQO1 and HO-1, which is consistent with its known effects on the Nrf2 pathway and provides a potential mechanism by which it could exert its therapeutic effects in preclinical models of epilepsy." (PMID 37940957, 2023). "In mice with epilepsy, treatment with SFN resulted in a notable elevation in the levels of Nrf2, NQO1, and HO‐1 in brain tissue (Sandouka and Shekh‐Ahmad 2021)." (PMID 40061295, 2025). "This activation leads to enhanced antioxidative enzyme expression (GSH‐Px, HO‐1, NQO1) and decreased OS markers (MDA), suggesting a mechanistic pathway for cognitive function improvement in epilepsy models." (PMID 40061295, 2025). "Our results revealed that in the cortex, the expression of Nrf2 and its target genes NQO1 and HO-1 was higher in the females compared to male rats at the chronic phase of epilepsy (i.e. 6–12 weeks post-SE), but not during epileptogenesis." (PMID 36600279, 2023).
Insulin resistance (7 papers, 2012 to 2024). Increased resistance towards insulin, that is, diminished effectiveness of insulin in reducing blood glucose levels. "NQO1 confers protection against metabolic disorders that are associated with chronic inflammation and insulin resistance." (PMID 33298924, 2020). "Thus, overexpression of HO-1 reduces inflammation by decreasing the activation of pro-inflammatory transcription factors, whereas genetic knockdown of NQO1 is associated with insulin resistance in obese mice." (PMID 37834034, 2023). "NQO-1 reduction or knockout can result in an increase in insulin resistance in mice." (PMID 36432871, 2022). "A previous study has shown that a lack of NQO1 decreases NAD+ content in the liver and kidneys and increases insulin resistance, whereas enhanced NQO1 activation has been shown to increase NAD+ levels in cells and protect obese mice via enhanced glucose and lipid metabolism." (PMID 33925372, 2021). "To assess the impact of genetic overexpression of NQO1 at conferring protection from diet-induced insulin resistance, we used a fasting/feeding paradigm in which mice previously on either SD or HFD for 16 weeks were fasted for 24 h followed by a 3-h refeeding period with their respective diet." (PMID 33298924, 2020). "The insulin resistance in HepG2 cells can be improved by elevating the expression levels of nuclear factor erythroid 2-related factor 2 (Nrf2), superoxide dismutase (SOD), NADPH quinone oxidoreductase (NQO1), heme oxygenase-1 (HO-1), and glutathione peroxidase (GSH-Px)." (PMID 38671903, 2024). "To validate this results, we assessed the modulation of ICAM1, NQO1, IGFBP3, and THBS1 by POPs because, in addition to their role in cell adhesion, xenobiotic metabolism, angiogenesis, and cancer, these genes were reported to be related to adiposity, insulin resistance, and inflammation." (PMID 22262711, 2012).
kidney (7 papers, 2012 to 2023). "Inhibition of NQO1 activity by dicoumarol, the pharmacological NQO1 inhibitor, was shown to suppress urogenital cancer cell growth and potentiate cytotoxicity of doxorubicin and cisplatin." (PMID 29914576, 2018). "Higher expression levels of NQO1 mRNA were correlated with more advanced pathological stages in kidney renal papillary cell carcinoma and invasive breast carcinoma; In kidney chromophobe, kidney renal clear cell carcinoma, and pan-kidney cohort, NQO1 mRNA levels are lowest at SatgeII." (PMID 37583897, 2023). "HO-1 and NQO1 are markedly deceased in acute lung and kidney ischemia-reperfusion injury." (PMID 22784636, 2012). "In I/R induced kidney injury, to understand the involvement of ELF4 and whether this influences were related to OS and ERS, we assessed the change of OS index (SOD, CAT, and GSH-PX), OS related proteins (Nrf2, HO-1, and NQO-1), and ERS related proteins (GRP78, CHOP, and caspase-12)." (PMID 37474923, 2023).
acute myeloid leukemia (6 papers, 2011 to 2023). Acute myeloid leukemia (AML) is a group of neoplasms arising from precursor cells committed to the myeloid cell-line differentiation. "Other tumors, including acute myeloid leukemia and diffuse large B-cell lymphoma had lower NQO1 mutation frequency." (PMID 37583897, 2023).
acute pancreatitis (6 papers, 2018 to 2025). An acute inflammatory process that leads to necrosis of the pancreatic parenchyma. "This study provides new insights into the mechanism of pancreatic protection associated with the regulation of NOX activity by NQO1 activation and identifies new potential targets and drugs for the treatment and prevention of acute pancreatitis." (PMID 30584237, 2018). "The regulatory role of NQO1 for the alleviation of acute pancreatitis by reducing serum IL-1β was also reported." (PMID 40825682, 2025). "High-dose vitamin C alleviates pancreatic injury via the NRF2/NQO1/HO-1 pathway in a rat model of severe acute pancreatitis." (PMID 33158207, 2020). "In conclusion, this is the first study showing that the activation of NQO1 by dunnione reduces pancreatic inflammation by reducing oxidative stress in acute pancreatitis." (PMID 30584237, 2018). "This study is the first to demonstrate that modulation of the cellular NADPH:NADP+ ratio by enzymatic action of NQO1 protects acute pancreatitis through the regulation of NOX activity." (PMID 30584237, 2018). "First, the injection of caerulein in NQO1−/− mice showed a typical acute pancreatitis with histological staining." (PMID 30584237, 2018). "Therefore, DHA can exert positive modulatory effects on acute pancreatitis by inhibiting oxidative stress and inflammatory cytokine production by activating Nrf2 signaling to induce NQO1 and HO-1 expression in pancreatic acinar cells." (PMID 33158207, 2020). "We also investigated whether the modulation of the cellular NADPH/NADP+ ratio by the enzymatic action of NQO1 is protective against acute pancreatitis through the regulation of NOX activity." (PMID 30584237, 2018). "Furthermore, these results suggest that modulation of the NADPH:NADP+ ratio in cells by NQO1 may be a novel therapeutic strategy for acute pancreatitis." (PMID 30584237, 2018).
cardiac hypertrophy (6 papers, 2018 to 2023). "Wogonin can delay the progression of ventricular hypertrophy and remodeling by specifically targeting Nrf-2 and promoting the expression of downstream antioxidant genes HO-1 and NQO-1." (PMID 36661523, 2023). "Further studies are needed to verify that Wog specifically targets Nrf-2 to promote the expression of its downstream antioxidant genes Ho-1 and Nqo-1 and attenuates oxidative stress in cardiac hypertrophy." (PMID 34290825, 2021). "Subsequent RT-PCR indicated that MFE regulated the expression levels of genes responsive to cardiac hypertrophy (i.e., Myh-7, ANP) and oxidative stress (i.e., GR, GPx, and NQO-1)." (PMID 34579143, 2021).